RPL12P2 (ribosomal protein L12 pseudogene 2)
Synonyms: dJ441G21.1
Gene: Processed pseudogene on chromosome 6 (37,091,314 to 37,091,806, forward strand). Ensembl gene ENSG00000216412.
Diseases named in the same sentence as RPL12P2 in open-access papers:
RPL12P2 is named in the same sentence as 3 diseases in open-access papers, as found by Europe PMC text mining. Sharing a sentence is not in itself a finding about the gene and the disease.
RPL12P2 shares sentences with these, for which no sentence is quoted: restless legs syndrome (1 paper); schizophrenia (1); Tourette syndrome (1).